STAT1 (signal transducer and activator of transcription 1)
Diseases named in the same sentence as STAT1 in open-access papers (continued):
Sharing a sentence is not in itself a finding about the gene and the disease.
breast cancer (continued). "Thus, mammary tumors in STAT1-/- mice progress developmentally from intraepithelial neoplasia to carcinoma in a manner that is remarkably similar to the progression from ductal carcinoma in situ to invasive ductal carcinoma seen in the human disease." (PMID 22264274, 2012). "Since spontaneous ERα+/PR+ mammary tumors are rarely observed in mice, our findings also suggested that STAT1-/- mice may represent a relatively novel model for human ERα+/PR+ luminal breast cancer." (PMID 22264274, 2012). "Interestingly, the expression levels of STAT1 in the tumor-infiltrating stromal cells remain elevated, indicating that single-cell resolution analysis of STAT1 level in primary breast cancer biopsies is necessary for accurate assessment." (PMID 22264274, 2012). "Current dogma, based on gene expression analyses of intact breast cancer biopsies, holds that STAT1 mRNA levels are elevated in breast cancer tissues compared with normal breast tissues, leading to the hypothesis that STAT1 might facilitate tumor outgrowth." (PMID 22264274, 2012). "Mice lacking RAG2 alone did not develop mammary tumors, demonstrating that this phenotype is specifically associated with STAT1 deficiency." (PMID 22264274, 2012). "Together, the studies unequivocally defined STAT1 as a tumor suppressor in mammary cancer." (PMID 22185785, 2011). "Furthermore, treatment of human mammary tumor cells with cytostatic drugs has been shown to induce STAT1 activation, resulting in enhanced apoptosis." (PMID 22185785, 2011). "We now report for the first time that loss of STAT1 alone is sufficient to cause pregnancy-associated mammary cancer in BALB/c mice, independent of any other transgenic oncogene." (PMID 22185785, 2011). "As a consequence, mammary cancer formation is increased in a Stat1−/− micro-environment, irrespective of whether the epithelial cells themselves express STAT1." (PMID 22185785, 2011). "Initial evidence for this hypothesis was provided by the analysis of STAT1 and IRF1 protein expression in primary mouse mammary tumor tissue: the levels of IRF1 protein correlated with the expression levels of STAT1." (PMID 22185785, 2011). "Therefore, the TNFAIP1/POLDIP2 SFGM is also potentially regulated by STAT1 and Sp1 as well as stimulated by interferon-gamma in breast cancer cells." (PMID 20158880, 2010). "This approach identified for the first time 3 novel lead compounds that competitively inhibit Stat3 binding to its pY-peptide ligand, that are selective for Stat3 vs. Stat1 and that also induce apoptosis preferentially of breast cancer cells lines with constitutively activated Stat3." (PMID 19274102, 2009). "We previously demonstrated that STAT1H tumors overexpressing the IFN/STAT1 pathway are resistant to Dox treatment and that constitutive expression of this pathway is predictive for response to adjuvant chemotherapy in patients with breast cancer." (PMID 19503789, 2009). "Interestingly, activated Etk has been reported to trigger apoptosis in breast cancer cells via Stat1 and p21." (PMID 19000305, 2008). "To test this hypothesis we stained normal breast and breast cancer sections using antibodies specific for STAT1, the key transcriptional activator of the interferon-response genes, and itself a protein over-expressed in response to interferon stimulation." (PMID 17868458, 2007). "Overall, in this study we demonstrate that the cell-autonomous pro-metastatic functions of PD-L1 in breast cancer cells are fully dependent on all four N-linked glycosylation sites of the protein, and that N-linked glycosylation of PD-L1 at specific sites leads to STAT3 and STAT1 activation." (PMID 37830552, 2023). "Furthermore, pSTAT3 gene signatures were correlated with PD-L1 expression in tumor cells and immune cells of breast cancer patient tumors, and the activated forms of STAT3 and STAT1 were significantly associated with the expression of PD-L1 in breast cancer patients." (PMID 37830552, 2023).
breast cancer (continued). "However, contradictory results have also been reported, showing that high STAT1 expression levels are found in some cancers and correlate with poor prognosis compared to those with low expression levels, such as breast cancer, glioblastoma, lymphoma, and renal cell carcinoma." (PMID 36061181, 2022). "In the current study, we demonstrate the apoptotic function of EGFR in metastatic breast cancer is dependent on STAT1 and we address the hypothesis that pharmacologic inhibition of MEK1/2 with trametinib will bias EGFR signaling toward a STAT1-dominated, apoptotic signaling pathway." (PMID 30250119, 2018). "STAT1 deficiency in MT/Shc313F/313F mammary tumours had no impact on tumour onset or growth." (PMID 28276425, 2017). "Thus the increase in STAT1 levels in the subset of breast cancer cases that exhibit low STAT1 expression in the neoplastic cells could be explained by selective upregulation of STAT1 transcription in the stromal cells alone." (PMID 27769057, 2016). "Therefore, if ER-positive (luminal A type) cancers have a higher level of expression of STAT1 than other breast cancer types, they may represent the best target group for STAT1-targeted approaches." (PMID 24728078, 2014). "Furthermore, increasing lines of evidence indicated their involvement in the oncogenesis of breast cancer and in resistance to endocrine therapy; however, there have been few studies on STAT1 in breast cancer, particularly relating to endocrine treatment resistance." (PMID 24728078, 2014). "However, it remains unclear whether the altered STAT1 levels were present in the breast cancer cells themselves or in stromal cells." (PMID 22264274, 2012). "Thus, the STAT1-/- mammary tumors are functionally similar to human ERα+/PR+ breast cancers." (PMID 22264274, 2012). "Pathologically, the STAT1-/- mammary tumors progress from a preneoplastic state classified as mammary intraepithelial neoplasia to adenocarcinoma, mirroring the progression of human breast cancer from atypical hyperplasia to ductal carcinoma in situ and finally to invasive carcinoma." (PMID 22264274, 2012). "Therefore, an increase in STAT1 mRNA levels in the subset of breast cancer cases that exhibit low STAT1 expression in the neoplastic cells could be explained by a selective upregulation of STAT1 transcription in the stromal cells alone." (PMID 22264274, 2012). "Finally, analyses using two other statistical methods (sigClust and consensus clustering) also supported the conclusion that STAT1-/- ERα+ mammary tumors grouped more consistently and reproducibly with human luminal breast cancers than any other mouse mammary tumor model." (PMID 22264274, 2012). "Since STAT1 is uniformly expressed in the luminal epithelial cells of breast tissues from normal healthy individuals, the observation that a large subset of breast cancer cases exhibit low levels of STAT1 expression suggests that STAT1 may be downregulated specifically in the neoplastic cells." (PMID 22264274, 2012). "Hence, mammary tumors are partially able to escape immune control by down-regulating STAT1." (PMID 22185785, 2011). "The Janus kinase 1 (JAK1)/STAT1/IRF1 signaling pathway, which is activated by the binding of IFN-γ to IFN receptors, prevents mammary cancer formation by maintaining growth control." (PMID 41567365, 2026). "For breast cancer, QRT has been studied in the context of immunotherapy by modulating the JAK/STAT1 pathway where QRT can inhibit tumour immune escape mechanisms, thereby improving T cell recognition and response against tumour cells." (PMID 40084006, 2025). "In breast cancer, JMJD8 inhibits type I IFN signaling by blocking STING-TBK1 complex formation, and progesterone receptor (PR) interacts with STAT1 to suppress IFN-induced STAT1 phosphorylation." (PMID 41050070, 2025).
breast cancer (continued). "For MLKL gene expression, IFNγ upregulates MLKL mRNA in breast carcinoma and cervical carcinoma cells, and IRF1 or STAT1 knockout reverses IFNγ-mediated induction of the MLKL mRNA level." (PMID 38671928, 2024). "The JAK/STAT1 pathway activated by IFN-γ positively correlates with PD-L1 expression and plays a critical role in breast cancer immune escape." (PMID 37764768, 2023). "STAT1 signaling pathway has been found to down-regulate quinone oxidoreductase 1 (NQO1), which function as ROS scavengers in breast cancer." (PMID 37748319, 2023). "Overall, our study indicates that N-linked glycosylation of PD-L1 is required for the ability of PD-L1 to induce cell-autonomous pro-metastatic activities in breast cancer cells, mainly by regulating the activation of STAT3 and STAT1." (PMID 37830552, 2023). "Chemical inhibition of STAT1 signaling in MCT-primed breast cancer sensitizes TNBC to ICB treatment, which underscores the STAT1’s role in modulating TIME." (PMID 37055410, 2023). "The results showed that the expression of SLC31A1 was significantly positively correlated with immune markers in breast cancer, especially for STAT3 of Th17 (r = 0.382, p < 0.001), STAT1 of Th1 (r = 0.358, p < 0.001), and CCR8 of Treg (r = 0.304, p < 0.001)." (PMID 37275369, 2023). "IL-6-induced p-STAT1 and p-STAT3 were lower in naïve CD4+ T cells from breast cancer patients compared to healthy donors." (PMID 37741983, 2023). "In breast cancer cells, CD24 expression has been shown to downregulate total and phosphorylated levels of STAT1." (PMID 36016357, 2022). "Mechanistically, miR-155 overexpression in breast cancer cells upregulated their CXCL9/10/11 production, which was mediated by SOCS1 inhibition and increased phosphorylated STAT1 (p-STAT1)/p-STAT3 ratios." (PMID 35925680, 2022). "Here, we demonstrate that UBR5 is required for IFN-γ-induced PD-L1 expression in breast cancer, and that transactivation of PDL1 gene expression by UBR5 is mediated through the PKR/STAT1/IRF1 pathway." (PMID 35836797, 2022). "STAT1 expression has been reported to be increased in EGFR-positive and HER2-positive breast cancer patients, and relapse-free survival was found to be decreased in high-risk breast cancer patients." (PMID 35781872, 2022). "Recent reports indicated that SHC1 was a key driver of breast cancer initiation, and the SHC1 adaptor simultaneously balanced Stat1 and Stat3 activity to promote breast cancer immune suppression." (PMID 35935986, 2022). "It was also demonstrated that induction of ACTA2 by EGFR and HER2 dimerization is regulated through a JAK2/STAT1 signaling pathway and that abnormal ACTA2 expression accelerates the invasiveness and metastasis of breast cancer cells." (PMID 34211976, 2021). "Indeed, we previously showed that an increased ratio of active STAT1/STAT3 in breast tumors is associated with improved immune surveillance, increased production of inflammatory cytokines, and enhanced sensitivity to immune checkpoint inhibitors in breast cancer." (PMID 33807608, 2021). "STAT1 was the first member of the STAT family to be identified and is commonly regarded as a tumor suppressor protein in malignant tumors such as breast cancer, melanoma, and leukemia." (PMID 35003395, 2021). "EGFR and HER2 dimerization modulated ACTA2 through the JAK2/STAT1 signaling pathway and ACTA2 gene abnormalities accelerated the invasion and metastasis of breast cancer cells." (PMID 34179721, 2021). "In conclusion, Que plays a synergistic role in killing breast cancer cells and promoting apoptosis by regulating the expression of IFNγ-R, p-JAK2, p-STAT1 and PD-L1 in the JAK/STAT1 signaling pathway and promoting the regulation of γδ T cells." (PMID 34838003, 2021). "Fludarabine, another inhibitor of STAT1 phosphorylation, also revealed effectiveness in the suppression of IDO activity in breast cancer and melanoma cell lines." (PMID 34201791, 2021).
breast cancer (continued). "We demonstrated for the first time the proapoptotic effect of Que on different breast cancer cells and explored the mechanisms by which Que influences immunity by affecting the JAK/STAT1 signaling pathway." (PMID 34838003, 2021). "Elevated interferon signaling and STAT1 and active pSTAT1 and HER2 expression in ER-positive FOXM1 inhibitor-resistant breast cancer would likely provide an immune suppressive environment that would allow the cancer to progress." (PMID 34944900, 2021). "Here we show that treatment of CAMA-1 and MCF-7, two ER-positive and luminal-like breast cancer cell lines, with Smac mimetic LCL161 and TRAIL induces IFN signaling with phosphorylation of STAT1." (PMID 33770100, 2021). "The STAT family comprises seven TFs, STAT1, STAT2, STAT3, STAT4, STAT5a, STAT5b, and STAT6, among the most critical TFs in breast cancer." (PMID 34488773, 2021). "The expression level of STAT1 was high in breast cancer tissues, while the expression level of MS4A4A was relatively low in breast cancer tissues." (PMID 34020650, 2021). "Upregulated and phosphorylated STAT1 and STAT3 are known to promote breast cancer progression and drug resistance and high levels are associated with poor outcomes and shorter survival in a variety of cancers." (PMID 34944900, 2021). "The functions of STAT1, STAT3, STAT5, and STAT6 in breast cancer formation, progression, prognosis and prediction have been documented." (PMID 32754201, 2020). "Overall, this thorough study strongly suggests IFN-I as a cancer stemness driver in breast cancer, SCC and GBM, involving activation of STAT1, STAT2, and STAT3." (PMID 32296435, 2020). "Analysis of STAT1 expression in different subtypes of breast cancer showed that, similar to PLSCR1, STAT1 was significantly upregulated in BLBC in the MEBTABRIC dataset." (PMID 32292520, 2020). "Breast cancer cells with high expression of CD44, one of cancer stem cell markers, express higher levels of STAT1 compared with cells with low CD44 expression." (PMID 30709063, 2019). "Recently, suramin has been shown to interfere with intracellular signalling proteins in the WNT pathway to inhibit the growth of breast cancer cells in a mouse xenograft model, and to target SH2 domains of STAT5a/b and STAT1." (PMID 31409229, 2019). "Although ODZ10117 inhibited the tyrosine phosphorylation of STAT3, it did not significantly affect other STAT family proteins, including STAT1, STAT5, and STAT6, in breast cancer cells and Hodgkin’s lymphoma cells." (PMID 31684051, 2019). "We have recently reported that dual inhibitions of STAT1 and STAT3 constitutively inhibit PD-L1 expression in human breast cancer cells." (PMID 30915120, 2019). "It has been previously reported that targeting upstream signals via dual inhibition of STAT1 and STAT3 completely downregulates PD-L1 expression in breast cancer cells." (PMID 31505846, 2019). "Together, the results demonstrate a suppressive role of miR-29c by targeting the TIMP3/STAT1/FOXO1 pathway in breast cancer cell proliferation, migration and invasion, and suggest that the loss of miR-29c might be a novel biomarker related to the progression of breast cancer." (PMID 29796115, 2018). "Taken together, these results demonstrated that induction of ACTA2 by EGFR and HER2 dimerization was regulated through a JAK2/STAT1 signaling pathway, and aberrant ACTA2 expression accelerated the invasiveness and metastasis of breast cancer cells." (PMID 28881584, 2017). "Similar studies showed that exosomes derived from CAF activated STAT1 in breast cancer cells through the receptor RIG-1; at the same time STAT1 activation further activated NOTCH3, which increased drug resistance in CSCs." (PMID 29194401, 2017). "In breast cancer, IRDS expression measured by a clinical classifier comprised of seven IRDS genes (STAT1, MX1, ISG15, OAS1, IFIT1, IFIT3, and IFI44) identifies patients whose cancers are resistant to chemotherapy and radiotherapy." (PMID 28279982, 2017).
breast cancer (continued). "Here, the authors show that tyrosine kinases engage scaffold protein Shc1 to promote immunosuppression in breast cancer by simultaneously activating STAT3 immunosuppressive signals and impairing STAT1-driven anti-tumour immune responses." (PMID 28276425, 2017). "We also analyzed the patterns of ACTA2 and STAT1 expression in HER2-negative and HER2-positive breast cancers from patients using the GEO database (GSE19615)." (PMID 28881584, 2017). "This study showed that the IRF8 promoter was frequently hypermethylated in primary breast cancers, and IRF8 served as a main downstream factor in the IFN-γ/STAT1 signaling pathway, with a possible role in enhancing the anti-tumor effect of IFN-γ." (PMID 28388578, 2017). "Taken together, these results demonstrated that dimerization of EGFR and HER2 activates the JAK2/STAT1 signaling axis and induces ACTA2 expression in breast cancer cells." (PMID 28881584, 2017). "Together these results demonstrate that STING pathway is involved in the transcriptional upregulation of type I IFNs triggered by genotoxic treatment of breast cancer cells, resulting in cell-autonomous activation of IFN/STAT1 signaling." (PMID 27791205, 2016). "Immunohistochemical analysis of total and ph-STAT1, and STAT3 were performed on tissue microarray of 384 breast cancer specimens." (PMID 27769057, 2016). "Real-time PCR and Western blot analyses were used to assess mRNA and protein levels of IFITM1, PLSCR1, STAT1, STAT2, and IRF-7 in AI-resistant MCF-7:5C breast cancer cells and AI-sensitive MCF-7 and T47D cells." (PMID 25588716, 2015). "The roles of STAT1 and STAT3 in breast cancer remain controversial since multiple studies have reported variable results between STAT isoform expression and clinical outcome, suggesting a degree of complexity in STAT signaling which is poorly understood." (PMID 24728078, 2014). "Others have shown that STAT1 and IRF1 are aberrantly expressed in some ER+ breast cancer tissues and cell lines and both have tumor suppressor properties." (PMID 24475282, 2014). "Expression levels of STAT1 and STAT3 transcript were analysed in 550 breast cancers from publicly available gene expression datasets (GSE2990, GSE12093, GSE6532)." (PMID 24728078, 2014). "This study aimed to investigate further the roles of STAT1 and STAT3 in endocrine sensitive and resistant breast cancer using both cell line models and clinical samples from breast cancer patients." (PMID 24728078, 2014). "Analysis of STAT1 and STAT3 protein expression in a series of 546 breast cancers also indicated that high expression of STAT3 protein was associated with improved survival (DMFS, p = 0.006)." (PMID 24728078, 2014). "Furthermore, the postulated disparity in kinetics of STAT1 signaling in breast cancer tumors may underlie the lack of linkage between pY-STAT1 levels and STAT1 mRNA expression." (PMID 24725474, 2014). "In breast cancer cells, PRL activates Jak2, stimulates phosphorylation of Stat1, Stat3 and Stat5 and induces cell proliferation." (PMID 23317095, 2013). "In breast cancer cell lines, IFNγ down-regulates S100A7 expression, through STAT1 transcriptional activity." (PMID 23285311, 2012). "However, since the immunodeficient RAG2-/- mice never developed mammary tumors and the loss of STAT1 expression was observed only in the neoplastic cells of human breast cancers, we hypothesized that STAT1 might act as a cell-intrinsic tumor suppressor in mammary epithelium." (PMID 22264274, 2012). "The experiments characterize STAT1/IRF1 as a key growth inhibitory and tumor suppressive signaling pathway that prevents mammary cancer formation by maintaining growth control." (PMID 22185785, 2011). "The effect of STAT1 loss is also not restricted to tumors that display a particular pattern of expression of the estrogen receptor (ER): 7/13 of the spontaneously evolving Stat1−/− mammary cancers were ER+, while the remaining cases did not express detectable levels of the ER protein." (PMID 22185785, 2011).